ZSWIM9 (zinc finger SWIM-type containing 9)
Synonyms: C19orf68; LOC374920
Tractability: PROTAC: UniProt records ubiquitination sites on it; ubiquitination databases record sites on it.
Gene: Protein-coding gene on chromosome 19 (48,170,645 to 48,197,624, forward strand). Ensembl gene ENSG00000185453.
Subcellular location (Human Protein Atlas): Nucleoplasm
Gene Ontology:
Molecular function: protein binding
Genetic constraint (gnomAD): Loss-of-function variants: 11 observed, 21.28 expected, observed/expected ratio (o/e) 0.52, 90% interval 0.32 to 0.86. The synonymous counts are far from expectation, so gnomAD's model fits this gene poorly and the ratio says little. Missense variants: 1,070 observed, 1,030.1 expected, observed/expected ratio (o/e) 1.04, 90% interval 0.99 to 1.09. Synonymous variants: 562 observed, 470.08 expected, observed/expected ratio (o/e) 1.2, 90% interval 1.12 to 1.28.
Homologues: Orthologues: chimpanzee ZSWIM9 (99% identical), macaque ZSWIM9 (97% identical), dog ZSWIM9 (86% identical), pig ZSWIM9 (85% identical), rat Zswim9 (68% identical), mouse Zswim9 (67% identical), tropical clawed frog zswim9 (10% identical). Paralogues in human: SIAH1 (7% identical), SIAH2 (7% identical), SIAH3 (5% identical).
Diseases named in the same sentence as ZSWIM9 in open-access papers:
ZSWIM9 is named in the same sentence as 1 disease in open-access papers, as found by Europe PMC text mining. Sharing a sentence is not in itself a finding about the gene and the disease. The quoted sentences say what the papers report.
major depressive disorder (1 paper, 2023). An episode of depression lasting two or more weeks without an intervening episode of mania. "The same expression profile, i.e., a predicted decrease of GRIN2D and ZSWIM9 levels but increased SLC17A7 levels, was also associated with increased risk for AD, lower educational attainment, lower cognitive ability, and higher risk of major depressive disorder across several independent studies." (PMID 37794492, 2023).